TSLP (thymic stromal lymphopoietin)
Diseases named in the same sentence as TSLP in open-access papers (continued):
Sharing a sentence is not in itself a finding about the gene and the disease.
dermatitis (continued). "Notably, TSLP, mainly produced by epidermal keratinocytes and fibroblasts, could stimulate Th2 differentiation by promoting the migration of DCs to the epidermis, playing a central role in initiating Th2 type adaptive immune responses in AD skin inflammation." (PMID 38318507, 2023). "A high-fat diet (60% Kcal from saturated fat) has been shown to increase serum TSLP in C57BL/6 mice and exacerbate dermatitis in mice through upregulation of TSLP in NC/Nga mice that develop AD spontaneously." (PMID 37686715, 2023). "The result showed that depletion of i-Langerin+ dDCs in DTR mice after multiple diphtheria toxin (DT) injection significantly reduced thymic stromal lymphopoietin (TSLP) production in lesions and skin inflammation alleviation." (PMID 36304463, 2022). "IAId was able to suppress thymic stromal lymphopoietin (TSLP) and thereby inhibited calcipotriol (MC903)-induced AD-like dermatitis in mice." (PMID 36939800, 2022). "RG decreased the IL-6, thymic stromal lymphopoietin (TSLP), and TNF-α, and thymus and activation-regulated chemokine (TARC) expression; MAPKs activation; and dermatitis score in DNCB sensitized mice." (PMID 32326081, 2020). "Herein, we describe how the SPCM (+) cream suppresses the expression of cytokines, such as interleukin‐36 gamma (IL‐36γ) and thymic stromal lymphopoietin (TSLP), by protecting skin from proteases, as an alternative SC, and alleviates skin inflammation and itching." (PMID 40066914, 2025). "Stimulation with TNF-α/IFN-γ induces the production of pruritic cytokines and chemotactic chemokines in keratinocytes such as TSLP, IL-31, CCL17/TARC, and CCL22/MDC, further expanding skin inflammation with the recruitment of major T cell lineage, Th2 cells, resulting in epidermal damage." (PMID 37958804, 2023). "Next, we applied DMOG on the ear together with MC903 and investigated whether DMOG reduced the expression of TSLP and MC903-induced skin inflammation in vivo." (PMID 36983043, 2023). "In contrast to reactions in mice, MC903 did not upregulate TSLP in human keratinocytes, nor did it induce AD-like dermatitis in human skin." (PMID 36983043, 2023). "The expression of TSLP and IL-31 is elevated in the lesional skin of AD patients but not in other dermatitis." (PMID 37239060, 2023). "During skin inflammation, proteolytic enzymes trypsin and tryptase signal pro-inflammatory factors through PAR-2, leading to the production of chemokines and cytokines like TNFα, IL-4, and TSLP." (PMID 37511138, 2023). "In contrast, another study revealed a dual function of LCs in TSLP-promoted Tfh/Th2 differentiation that promoted Tfh differentiation in MC903-AD mouse model, and inhibited Tfh/GC response as well as suppressed Th2 skin inflammation and the atopic march in OVA-AD mouse model." (PMID 36304463, 2022). "Using semiquantitative analysis, except for DLE, TSLP was expressed in the stratum basale or the stratum spinosum in those dermatoses, and the difference between each dermatosis was not generally significant." (PMID 36046760, 2022). "In addition, the expression level of filaggrin was reduced by C3A and GGRT treatment, and the expression levels of dermatitis-related proteins, including KLK7, PAR-2, TSLP, and IL-4, were markedly recovered." (PMID 34946332, 2021). "Severe dermatitis induced by repeated DNFB-application under SPF condition in NC/Nga was alleviated partially in NC.h2b/nc and significantly in NC.h2b/b as shown by decreased epidermal expression levels of TSLP and serum levels of total IgE, TSLP, IL-18 and IL-33." (PMID 29416104, 2018). "Thus, TSLP may be an important determinant for promoting AD-like skin inflammation in the absence of keratinocyte STAT3." (PMID 38053996, 2023).
dermatitis (continued). "The relevance of overexpressed TSLP and deregulated MRGPRX2 activity in skin pathologies indicates that their synergy may have important ramifications for understanding and treatment of skin disorders, but also host-defenses organized by MRGPRX2 on the other end of the spectrum." (PMID 33429916, 2021). "This suggests that keratinocyte damage in the absence of SHARPIN may lead to release of TSLP and IL33, which initiate the dermatitis through the activation of ILC2 and basophils." (PMID 32687504, 2020).
allergic asthma (70 papers, 2010 to 2026). A asthma with a basis in a pathological type I hypersensitivity reaction. "Our data expands on these clinical findings, showing a significant correlation between RSV-induced TSLP and the subsequent development of viral-associated allergic asthma later in life in male mice, following early-life RSV-infection." (PMID 31076663, 2019). "The results showed that the expression levels of TSLP, IL-33, IL-4, IL-5, and IL-13 were higher in clusterB or gene clusterB than those in clusterA or gene clusterA, which suggested that clusterB or gene clusterB is highly linked to allergic asthma characterized by the Th2 immune response." (PMID 33763115, 2021). "TSLP, an epithelial-derived cytokine, plays a central role in initiating Th2-type immune responses in allergic asthma." (PMID 41259396, 2025). "Taken together, these findings suggest that DEP exposure results in epithelial-derived TSLP expression in patients with severe allergic asthma." (PMID 38672419, 2024). "DEPs activate Ahr located in the epithelial cell cytoplasm in patients with severe allergic asthma, thereby enhancing mRNA expression of epithelial alarmins in the airways, including TSLP, IL-33, and IL-25." (PMID 38672419, 2024). "In patients with allergic asthma, it was reported a correlation between the level of immunopositive staining for TSLP in bronchial biopsies and airway eosinophilia 24 hours after allergen exposure." (PMID 38415254, 2024). "Proof-of-concept studies have examined mechanisms of TSLP using inhaled allergen challenges in patients with mild allergic asthma." (PMID 38672419, 2024). "IL-33 and thymic stromal lymphopoietin (TSLP) further amplify these responses by promoting the release of type 2 cytokines and enhancing IgE production, a hallmark of allergic asthma." (PMID 39902079, 2024). "Nonetheless, in addition to lower costs of small molecules versus biologics, a topical application appears favorable since TSLP drives the initial sensitization for allergic asthma locally in the skin." (PMID 38877290, 2024). "Numerous studies using murine models have provided major insights regarding the role of TSLP in the development of allergic asthma." (PMID 37108740, 2023). "In allergic asthma, by activation of DCs, TSLP promotes the differentiation of TH2 lymphocytes secreting T2 cytokines targeting B cells, eosinophils, mast cells and airway smooth muscle cells." (PMID 37628907, 2023). "The efficacy of anti-TSLP antibodies (Tezepelumab) has been extensively demonstrated in treating refractory severe allergic asthma." (PMID 37508573, 2023). "Targeting TSLP in the airways of mice prior to OVA allergic sensitization reduces airway inflammation, suggesting that TSLP is a promising therapeutic target for allergic asthma." (PMID 36245744, 2022). "An anti-human TSLP monoclonal antibody (AMG157/tezepelumab) that prevents the interaction of TSLP with its receptor was shown to significantly reduce allergen-induced airway responses and airway inflammation in patients with mild allergic asthma." (PMID 36292755, 2022). "We thus aimed to investigate the role of TSLP in the allergen cutaneous sensitization occurring at different anatomic depth of mouse skin and the subsequent development of allergic asthma." (PMID 36050303, 2022). "To further reveal the relationship between m6A patterns and allergic asthma, we investigated the correlation between m6A patterns and thymic stromal lymphopoietin (TSLP), interleukin (IL)-33, IL-4, IL-5, and IL-13." (PMID 33763115, 2021). "When purified from patients with allergic asthma, myeloid dendritic cells can be primed to induce Th2 cell expansion by a combination of TSLP and dermatophagoides pteronyssinus-derived allergens." (PMID 33922072, 2021). "In allergic asthma, TSLP activates DCs and promotes the homeostasis shift of Th1/Th2 into Th2, which subsequently results in airway remodeling and sustained airway hyperresponsiveness (AHR)." (PMID 34522948, 2021).
allergic asthma (continued). "Type 2 immune responses to allergen exposure play crucial roles in the pathogenesis of allergic asthma, which is initiated by epithelium-derived cytokines including IL-33, IL-25 and thymic stromal lymphopoietin (TSLP)." (PMID 33607992, 2021). "In patients with allergic asthma, TSLP also up-regulates basophil expression of the ST2 receptor of IL-33 and IL-17RB receptor of IL-25, thus incrementing the susceptibility of basophils to other alarmins." (PMID 33922072, 2021). "Binding of the viral capsid to these innate receptors such as TLR-4 leads to activation of innate alarmins such as those seen during allergic asthma such as IL-25, IL-33, and thymic stromal lymphopoietin (TSLP)." (PMID 35387053, 2021). "As a key switch in triggering Th2 responses in allergic asthma, TSLP anchors are typically induced/promoted/activated by damaged epithelial cells." (PMID 34522948, 2021). "Several studies have identified an important role of airway epithelial-derived cytokines, recognized as epithelial alarmins, including interleukin (IL)-25, IL-33, and thymic stromal lymphopoietin (TSLP) in the pathogenesis of allergic asthma." (PMID 31581688, 2019). "In our group, we revealed that IgE and TSLP levels in the peripheral blood of children with allergic asthma are higher than those in normal children." (PMID 29670037, 2018). "TSLP anchors at the epithelial cells and acts as a key switch to trigger Th2 responses in allergic asthma, usually primarily produced by the damaged epithelial cells." (PMID 27467143, 2016). "For example, TSLP knockout mice fail to develop an inflammatory lung response to inhaled antigens in a murine model of allergic asthma." (PMID 27378934, 2016). "Production of thymic stromal lymphopoietin (TSLP) in keratinocytes is essential in promoting allergic sensitization through an impaired skin barrier and eventual development of allergic asthma." (PMID 26225992, 2015). "Collectively, our data suggest a pro-migratory function of TSLP in ASM remodeling and provides better rationale for targeting TSLP/TSLPR pathway for therapeutic approaches in allergic asthma." (PMID 23892442, 2013). "One recent report demonstrates that neutralization of TSLP can inhibit airway remodeling in a murine model of allergic asthma induced by house dust mites." (PMID 24167583, 2013). "As an epithelium-generated cytokine, TSLP is produced primarily by damaged epithelial cells and under specific conditions in the immune system to induce Th2 responses in allergic asthma." (PMID 23300949, 2013). "Thymic stromal lymphopoietin (TSLP) is a pro-allergic, IL-7-like hematopoietic cytokine that has been shown to be necessary for the development of allergic asthma in some animal models." (PMID 23892442, 2013). "In the present study, the role of TSLP in the pathogenesis of airway remodeling in chronic allergic asthma was investigated using a chronic HDM-induced mouse model." (PMID 23300949, 2013). "We aimed to dissect the influence of TSLP on immunosuppressive activities of Treg and its potential consequences in human allergic asthma." (PMID 20230634, 2010). "Furthermore, the intranasal administration of PN has been shown to activate the MAPKs pathway and induce the production of TSLP and IL-25 independently of the IL-1R1/MyD88 signaling in a mouse model of allergic asthma." (PMID 39199175, 2024). "Thus, we treated BMDMs with various allergic asthma-related cytokines, including TSLP, IL-33, IL-13, and IL-4." (PMID 38177117, 2024). "Also, primary TSLP-mediated sensitization for allergic asthma happens in the skin in the context of AD." (PMID 38877290, 2024). "Exposure to low concentrations of particulate matter and DEP has been shown to induce upregulated TSLP expression at the mRNA and protein levels in dendritic cells and HBECs during a T2 response in allergic asthma or in an innate immune response in bronchial asthma." (PMID 38672419, 2024).
allergic asthma (continued). "Furthermore, in patients with allergic asthma, stimulation of peripheral basophils with TSLP results in upregulation of the activation marker CD203c, type 2 cytokine production, histamine release and eotaxin-mediated cellular migration responses." (PMID 37108740, 2023). "Our work shows a differential requirement for TSLP in these two contexts, and identifies an important function for IL-1β, which is independent of TSLP, in promoting allergen sensitization and subsequent allergic asthma." (PMID 36050303, 2022). "ClusterB was highly linked to the Th2 immune response and had higher expression levels of TSLP, IL-33, IL-4, IL-5, and IL-13, which indicated that clusterB may be related to allergic asthma." (PMID 33763115, 2021). "Intranasal, therapeutic administration of IFNL2/3 in a murine model of Th2-driven allergic asthma mitigated lung pathology and diminished levels of epithelial secreted Th2 cytokines, thymic stromal lymphopoietin (TSLP) and IL-33 in the bronchoalveolar lavage fluid." (PMID 34899712, 2021). "Activated platelets secrete IL-33, Dkk-1, and 5-HT or overexpress CD40L on the cell surfaces to induce Type 2 immune response or interact with TSLP-stimulated myeloid DCs through the RANK-RANKL-dependent manner to tune the sensitization stage of allergic asthma." (PMID 34440807, 2021). "Studies using adoptively transferred models of allergic asthma demonstrated that exogenously or ectopically expressed proallergic cytokines such as TSLP, TNF family cytokine TLI1 (Tnfsf15), and IL-25 promoted airway inflammation by increasing Th9 cell differentiation and IL-9 production." (PMID 33748292, 2021). "TSLP is a cytokine that plays a critical role in development of allergic asthma in AECs by functioning through the TSLP receptor (TSLPR) on myeloid DCs, which then triggers a second round of inflammatory cytokine secretion in RSV-infected tissues, causing lung damage." (PMID 31572372, 2019). "Altogether, the present data suggest that TSLP influences the development of mast cells and that mast cell-derived TSLP may contribute to allergic asthma." (PMID 31191511, 2019). "Our findings reveal a pro‐inflammatory role of airway ECs through a TLR2‐dependent TSLP production, which may have implication for treating allergic asthma." (PMID 30184256, 2018). "In a double-blind, placebo-controlled study, treatment with a human mAb to TSLP resolved airway inflammation and attenuated allergen-induced bronchoconstriction, findings consistent with TSLP as a therapeutic target in patients with allergic asthma." (PMID 28583446, 2017). "Similarly, dsRNA or rhinovirus infection enhances in vivo TSLP release in the airways of animal models of allergic asthma." (PMID 25546419, 2014). "Our study suggested that downregulating TSLP levels in asthmatic airway may benefit patients with chronic allergic asthma by reducing airway inflammation and improving lung function, with the potential to inhibit airway remodeling." (PMID 23300949, 2013). "Previous studies demonstrated that the neutralization of TSLP could inhibit airway remodeling in a murine model of allergic asthma induced by dust mites." (PMID 24167583, 2013). "Also, TSLP activation of basophils in allergic asthma patients is IL-3 dependent." (PMID 31941161, 2020). "TSLP is believed to be a systemic driver for bronchial hyperresponsiveness since blockade of TSLP signaling or inducible gene deletion of TSLP in mice keratinocytes prevents occurrence of the atopic march, suggesting a potential direct link between AD and allergic asthma and/or allergic rhinitis." (PMID 28791291, 2017). "Moreover, it could be released from AEC in response to virus-induced injury (together with other Th2-promoting cytokines such as IL-25 and TSLP) and might thus help to drive airway inflammation in acute exacerbations of allergic asthma." (PMID 25264520, 2014). "Thus, TSLP appears to be a critical and essential factor in the context of allergic asthma." (PMID 23300949, 2013).
allergic asthma (continued). "The allergic asthma disease state was induced by the administration of 40 μg OVA (ovalbumin) and 1 μg human TSLP intranasally into mice in groups B, C, D, and E every other day for two weeks, while mice in group A received PBS treatment as a sham control." (PMID 41294800, 2025). "The allergic asthma disease state was induced by the administration 10 μg OVA (ovalbumin) and 1 μg human TSLP intranasally into these mice every other day for two weeks." (PMID 39726595, 2024). "In contrast, in an allergic asthma model using the three different allergens HDM, OVA and Alternaria alternata, increased TLR2 and thymic stromal lymphopoietin (TSLP) levels in the lungs of challenged mice were found." (PMID 37426425, 2023). "We provide experimental evidence that in these two contexts, epidermal keratinocyte-derived TSLP plays either a major or only a partial role for HDM skin sensitization and the subsequent allergic asthma." (PMID 36050303, 2022). "A recent phase I randomized controlled trial evaluated the effectiveness of an anti-TSLP mAb, AMG 157, in reducing disease severity in patients with mild allergic asthma." (PMID 27156176, 2016). "Thymic stromal lymphopoietin (TSLP) is an IL-7-like, pro-allergic cytokine that has been shown to be necessary and sufficient for the development of allergic asthma." (PMID 23892442, 2013). "Thymic stromal lymphopoietin (TSLP) is believed to be a master regulator of Th-2-driven inflammation and the allergic asthma phenotype." (PMID 24063011, 2013). "The airway epithelium can produce several cytokines such as thymic stromal lymphopoietin (TSLP), IL-25 and IL-33 that play a critical role in induction of Th2 differentiation, nuocyte formation and induction of allergic asthma." (PMID 22347372, 2012). "Blocking thymic stromal lymphopoietin (TSLP) with tezepelumab reduced serum total IgE levels, improved FEF25–75 as well as attenuated the maximum % fall in FEV1 during the LAR in individuals with mild allergic asthma." (PMID 39941577, 2025). "Furthermore, it promotes allergen-induced upregulation of thymic stromal lymphopoietin (TSLP), IL-25, and IL-33 and type-2 reaction in murine models of allergic asthma." (PMID 38542187, 2024). "In murine allergic asthma model, repeated intranasal exposure to Cigarette Smoke Extract (CSE) induced TSLP production in bronchial epithelial cells and the administration of an anti-TSLP antibody to the same model attenuated CSE-enhanced leukocyte infiltration." (PMID 38415254, 2024). "Our study implicates a differential requirement for TSLP in these two contexts, and identifies an important function for IL-1β, which is independent of TSLP, in promoting allergen sensitization and subsequent allergic asthma." (PMID 36050303, 2022). "Eosinophilic non-allergic asthma is mediated by ILC2 production, induced by the release of IL-10, transforming growth factor beta (TGF-β) and alarmins, IL-25, IL-33, and thymic stromal lymphopoietin (TSLP)." (PMID 34835964, 2021). "In patients with allergic asthma, induction of type 2 airway inflammation mediated by TSLP is further potentiated by its negative impact on the immunomodulatory action of lung T regulatory (Treg) lymphocytes." (PMID 33922072, 2021). "Our data also indicate that the IL-33/ST2 axis is not involved in the TSLP-mediated model of airway inflammation and that IL-33 is not a general therapeutic target to prevent the allergic asthma once AD develops." (PMID 28490737, 2017). "We evaluated the levels of IL-33, IL-25 and TSLP, which are the upstream cytokines of ILC2s, in mice BALF when the airway epithelium was exposed to allergens to confirm whether Renifolin F inhibited OVA-induced allergic asthma by acting on ILC2s in mice." (PMID 35744915, 2022).